GTPBP10 (GTP binding protein 10)
Description:
May be involved in the ribosome maturation process. Complements an ObgE(CgtA) function in E.coli ribosome maturation. Plays a role of GTPase in vitro. When missing, disorganization of the nucleolar architecture is observed.
Synonyms: ObgH2; UG0751c10; DKFZP686A10121; FLJ38242; LOC101927446
Tractability: Small molecule: a structure with a bound ligand is known. PROTAC: ubiquitination databases record sites on it; its protein half-life has been measured.
Gene: Protein-coding gene on chromosome 7 (90,335,223 to 90,391,453, forward strand). Ensembl gene ENSG00000105793.
Subcellular location: Nucleus, nucleolus; Chromosome
Gene Ontology:
Molecular function: mitochondrial large ribosomal subunit binding; protein binding; RNA binding; rRNA binding; GTP binding; GTPase activity; magnesium ion binding
Biological process: mitochondrial large ribosomal subunit assembly
Cellular component: mitochondrial matrix; mitochondrion; chromosome; nucleolus
Genetic constraint (gnomAD): Loss-of-function variants: 10 observed, 13.29 expected, observed/expected ratio (o/e) 0.75, 90% interval 0.46 to 1.28. The upper end of that interval is the gene's LOEUF score, 1.28, which puts it in group 5 of 6, group 1 being the genes least tolerant of losing a copy. Missense variants: 156 observed, 178.53 expected, observed/expected ratio (o/e) 0.87, 90% interval 0.77 to 1. Synonymous variants: 58 observed, 61.29 expected, observed/expected ratio (o/e) 0.95, 90% interval 0.76 to 1.18.
Homologues: Orthologues: chimpanzee GTPBP10 (99% identical), macaque GTPBP10 (94% identical), chimpanzee GTPBP10 (93% identical), pig GTPBP10 (89% identical), dog GTPBP10 (86% identical), rabbit GTPBP10 (86% identical), guinea pig GTPBP10 (85% identical), rat Gtpbp10 (80% identical), mouse Gtpbp10 (78% identical), tropical clawed frog gtpbp10 (62% identical), zebrafish gtpbp10 (59% identical), Drosophila melanogaster CG10628 (44% identical), and 1 more. Paralogues in human: MTG2 (35% identical), GTPBP4 (21% identical), DRG1 (20% identical), DRG2 (18% identical).
Diseases named in the same sentence as GTPBP10 in open-access papers:
GTPBP10 is named in the same sentence as 5 diseases in open-access papers, as found by Europe PMC text mining. Sharing a sentence is not in itself a finding about the gene and the disease. The quoted sentences say what the papers report.
glioblastoma (1 paper, 2021). The most malignant astrocytic tumor (WHO grade IV). "GTPBP10 is a mitochondrial protein as a ribosome biogenesis factor correlated with multicentric glioblastoma." (PMID 33336077, 2021).
Huntington disease (1 paper, 2022). Huntington disease (HD) is a rare neurodegenerative disorder of the central nervous system characterized by unwanted choreatic movements, behavioral and psychiatric disturbances and dementia. "Our results suggested that the increased editing level of hsa-mir-10b_26_A_c might aggravate Huntington’s disease by repressing GTPBP10." (PMID 35210471, 2022). "GTPBP10 is often downregulated in HD and may deteriorate Huntington’s disease by affecting the synthesis of mitochondria and other related functions." (PMID 35210471, 2022).
GTPBP10 also shares sentences with these, for which no sentence is quoted: breast carcinoma (1 paper); cancer (1); tumor (1).